SWINGN (SWI/SNF complex interacting GAS6 enhancer non-coding RNA)
Synonyms: formerly LINC00565
Gene: Long non-coding RNA gene on chromosome 13 (113,923,052 to 113,928,991, reverse strand). Ensembl gene ENSG00000260910.
Diseases named in the same sentence as SWINGN in open-access papers:
SWINGN is named in the same sentence as 5 diseases in open-access papers, as found by Europe PMC text mining. Sharing a sentence is not in itself a finding about the gene and the disease. The quoted sentences say what the papers report.
lung carcinoma (1 paper, 2020). "The transcriptional activation of these genes is highly dependent on SWINGN expression, as we demonstrated by upregulating its levels by CRISPR activation (CRISPRa) in H226 lung cancer cells." (PMID 32071317, 2020).
tumor (2 papers, 2020 to 2025). "The unveiled role of SWINGN in the establishment of its regulatory network provides an epigenetic signature for tumor progression linked to SMARCB1 alterations." (PMID 32071317, 2020). "In agreement with the SWINGN pro-proliferative role associated with gene activation, the average expression of the signature was elevated in the tumor samples conforming cluster#2 as compared to cluster#1 samples, mostly composed of normal tissue samples." (PMID 32071317, 2020). "Moreover, H226 cells depleted of SWINGN presented a reduced tumor growth rate when injected into immunodeficient mice." (PMID 32071317, 2020). "We identify SWINGN, a lncRNA interacting with SMARCB1 exclusively in proliferating conditions, exerting a pro-oncogenic role in some tumor types." (PMID 32071317, 2020). "To get insight into SWINGN impact on GAS6 regulation in cancer we analyzed the correlation between SWINGN and GAS6 expression across samples of different tumor types of The Cancer Genome Atlas (TCGA)." (PMID 32071317, 2020). "SWINGN (also known as LINC00565) has recently been characterized as a functionally relevant long non-coding RNA that interacts with SWI/SNF chromatin remodeling complexes and modulates a tumor-promoting transcriptional program, including activation of GAS6 and other oncogenic genes." (PMID 41467176, 2025).
cancer (1 paper, 2020). A tumor composed of atypical neoplastic, often pleomorphic cells that invade other tissues. "In line with the oncogenic role of these genes, we observed a decrease in proliferation of H226 cells when either PDGFRB or COL1A1 were inhibited, additive to the effect achieved with GAS6 downregulation alone, supporting the existence of a SWINGN-dependent oncogenic hub in this cancer type." (PMID 32071317, 2020). "We hypothesized that the subset of genes co-regulated by SWINGN and SMARCB1 might contribute to the observed role of the lncRNA in promoting the proliferation of cancer cells." (PMID 32071317, 2020).
SWINGN also shares sentences with these, for which no sentence is quoted: ovarian carcinoma (3 papers); gastric cancer (1).